PDCD4 (programmed cell death 4)
Diseases named in the same sentence as PDCD4 in open-access papers (continued):
Sharing a sentence is not in itself a finding about the gene and the disease.
tumor (continued). "Extensive research has revealed that miR-21 is involved in proliferation, the cell cycle, metastasis and the chemosensitivity of tumor cells by targeting several tumor suppressor genes, including PTEN, MARCKS, PDCD4 and Cdc25A." (PMID 24260069, 2013). "We report here a strong correlation between low expression of PDCD4 and high expression of Bcl-xL in adult de novo GBM, GBM tumor initiating cells, and established GBM cell lines." (PMID 23965755, 2013). "In order to further explore the link between PDCD4 and Bcl-xL we examined a panel of established GBM cells lines and patient-derived tumor initiating cells (TICs)." (PMID 23965755, 2013). "Our data identify Bcl-xL as a target of PDCD4 whose elevated levels contribute to high chemoresistance in GBM, thus providing a novel treatment option for this aggressive tumor." (PMID 23965755, 2013). "The programmed cell death 4 (PDCD4) protein is induced in animals during apoptosis and functions to inhibit translation and tumor promoter-induced neoplastic transformation." (PMID 24041411, 2013). "One is programmed cell death 4 (PDCD4), a novel suppressor of tumourigenesis, tumour progression and invasion." (PMID 24106980, 2013). "This miRNA appears over expressed in different tumor samples and targets PTEN, PDCD4, TPM1, and Maspin human genes, promoting growth, migration, and invasion in different tumor types." (PMID 23251139, 2012). "These miRNAs have been largely studied for their functional consequences: miRNA-21 is known to be upregulated in several tumor entities and targets known tumor suppressive genes like PTEN and PDCD4." (PMID 21110877, 2010). "We further examined the effect of EIF4G1 on the expression of PDCD4, a key tumor suppressor protein interacting with EIF4G1 and controlling tumor growth and invasion." (PMID 20398343, 2010). "Using Programmed Cell Death 4 (PDCD4) EIF4A1 inhibits translation initiation and acts as a tumor suppressor by forming a complex." (PMID 21114830, 2010). "This reduction may suppress tumor-related processes such as cell proliferation and invasion by restoring function to tumor suppressor genes like PTEN and PDCD4, which are typically inhibited by miR-21." (PMID 38689139, 2025). "miR-21 is one of the most highly expressed miRNAs in PDAC and acts as an oncomiR by repressing genes with tumor suppressor functions such as PTEN, PDCD4, and TPM1, thus enhancing tumor growth and gemcitabine resistance, and, therefore, is a potential diagnostic and therapeutic target." (PMID 40699746, 2025). "In breast cancer, PRMT5 promotes tumor growth by methylating key substrates: it stabilizes KLF4 by inhibiting its ubiquitylation, leading to Bax downregulation and oncogene upregulation, and it methylates PDCD4, abolishing its tumor-suppressive function." (PMID 41204384, 2025). "Studies have shown that PDCD4 can upregulate the expression of E-Cadherin while decreasing the expression of EMT markers such as N-Cadherin and Vimentin, thereby inhibiting the migration and invasion ability of tumor cells." (PMID 40275278, 2025). "Furthermore, miR-21 is upregulated in various cancers, including EC, where it targets tumor suppressor genes such as PDCD4 and TIMP3, resulting in enhanced tumor cell proliferation and survival." (PMID 39944625, 2025). "In addition, miR-21 is also implicated in the development of chemotherapy resistance, as it is either directly involved in the regulation of tumor suppressor genes such as PTEN, PDCD4, and SMAD7 or indirectly involved in apoptosis inhibition." (PMID 38542098, 2024). "In lymphocytic leukemia, various aberrant signaling pathways in tumor microenvironment, including ZAP-70 protein, MAPK, and STAT3, stimulate the expression of post-translational regulator microRNA (miR-21) and other tumor suppressor genes (PTEN, PDCD4, and PIAS3)." (PMID 38590645, 2024). "MiR-21 promotes tumor growth by targeting tumor suppressors such as PTEN and PDCD4." (PMID 39858410, 2024).
tumor (continued). "Additionally, other blood markers such as T-cell factor 4 (TCF4), programmed cell death 4 (PDCD4), and circulating lymphocytes have all shown predictive potential for favorable tumor response and prognosis in patients with LARC undergoing nCRT." (PMID 39845322, 2024). "It targets nearly 30 genes, including tumor suppressors such as CDK2AP1, Pdcd4, and BCL2." (PMID 38790924, 2024). "miR-21-knock out reduced tumour development in vivo by negatively regulating the expression of Spry1, Pten, and Pdcd4, but miR-21-null mice did not have any other phenotypic anomalies." (PMID 39456841, 2024). "Related to multiple cancers, miR-21 targets and inhibits the tumor-related genes of programmed cell death 4 (PDCD4), and phosphatase and tensin homolog (PTEN); it is involved in tumor angiogenesis, which is closely related to tumor cell proliferation, invasion, and drug resistance." (PMID 35913675, 2023). "The expression of PDCD4 and PTEN might increase tumor apoptosis since the proteins are involved in growth arrest and apoptosis." (PMID 36925699, 2023). "On the same basis, programmed cell death 4 (PDCD-4) is one of the tumor suppressor genes that halts cancer cells’ growth and metastasis and is often reported to be downregulated in many cancer types that lead to tumor progression, promotion, and proliferation." (PMID 37513415, 2023). "In addition, it has been shown that miR-21-5p exerts its oncogenic role by targeting multiple tumor suppressor genes, such as Bcl-2, TPM1, PDCD4, and PTEN." (PMID 37444533, 2023). "It has been widely demonstrated that miR-21 can function as an oncogene, increasing tumor cell migration and invasion by directly targeting phosphatase and tensin homolog deleted from chromosome 10 (PTEN), RECK, and programmed cell death 4 (PDCD4)." (PMID 38139236, 2023). "Finally, when the CRISPR-Cas13a system was delivered by the CHAIN in vivo, it knocked down the targeted oncogene miR-21, restored PDCD4 and RECK, crippled downstream MMP-2, and eventually suppressed tumor growth." (PMID 37284454, 2023). "In total, we think that the decreased expression of MTHFR expression caused by the miR-22-3p and miR-149-5p mimic might inhibit the promoter methylation of TP53INP1 and PDCD4, thereby increasing TP53INP1 and PDCD4 expression and tumor suppression." (PMID 35723348, 2022). "Up-regulated miR-21 directly down-regulated programmed cell death 4 (PDCD4), a tumor suppressor; inhibition of PDCD4 suppressed downstream E-cadherin expression and promoted β-catenin/TCF-dependent transcription of c-Myc and plasminogen activator, urokinase receptor (uPAR)." (PMID 36497250, 2022). "Indeed, many studies have demonstrated that miR-21 has a central role in tumor initiation and progression by targeting critical tumor suppressive genes, such as PTEN or PDCD4." (PMID 36359921, 2022). "MiR-21 suppressed the action of various apoptotic and tumor suppressor genes including phosphatase and tensin homolog (PTEN), programmed cell death 4 (PDCD4), and tropomyosin 1 (TPM1) leading to an induction of cancer cell proliferation, and migration, as well as inhibiting apoptosis." (PMID 35684480, 2022). "Several other important tumor suppressor and oncogenic targets were detected for miR-21 in tumors of the head and neck, including Ras, HNRPK, reversion inducing cysteine rich protein with kazal motifs (RECK)andprogrammed cell death 4 (PDCD4)." (PMID 35898889, 2022). "It was concluded that the tumour suppressive effects of MEG3 were by sponging (binding and inactivating) miRNA-141 activity and expression, thereby preventing the microRNA from suppressing the expression of PDCD4." (PMID 35847932, 2022). "Additionally, several studies also indicate that miR-21 can modulate the chemosensitivity of cancer cells by targeting tumor-suppressors such as PTEN, programmed Cell Death 4 (PDCD4), and FasL via serum miR-21." (PMID 34572835, 2021).
tumor (continued). "In both neoplastic and non-neoplastic disease, the down regulation of miR-21 increased the rate of cell death, the exact target of this is unknown, though possibilities are HIF-1α, PTEN, and PDCD4." (PMID 33712063, 2021). "Among these miRNAs, miR-21 has been extensively investigated in different cancers where it was shown to target important tumor suppressors such as, for example, PTEN, SPRY2, TIMP3, PDCD4, RECK, and STAT3, and thus to behave as one of the most important oncogenic miRNAs (oncomiR) identified to date." (PMID 34638467, 2021). "Our data suggested that the survival benefit of PDCD4 in intracranial metastases is present regardless of where PDCD4 is expressed in the tumor cells (either nuclear or in the nucleus/cytoplasm) or stroma." (PMID 33801444, 2021). "Programmed cell death 4 (PDCD4), a well-documented tumor suppressor, could inhibit tumor cell proliferation, migration and invasion at the transcriptional and translational levels." (PMID 33537101, 2021). "The upregulation of miR-21, for instance, suppresses the tumor suppressor PDCD4 expression which fails to modulate NF-κB signaling while upregulated miR-9 provides a countermeasure by repressing NF-κB expression." (PMID 32664401, 2020). "It has recently been described that cytotoxic T cells lacking PDCD4 expression show increased expression of effector molecules and display superior tumor control." (PMID 32726622, 2020). "The upregulation of miR-21 promotes a pro-inflammatory response in macrophages by repressing the tumor suppressor PDCD4 expression which then fails to modulate NF-κB signaling." (PMID 32664401, 2020). "Furthermore, miR-21 can downregulate several tumor suppressor genes e.g., PDCD4, MARCKS, and RECK metalloproteinase inhibitor, TPM1 and hence stimulating tumor initiation, invasion, and intravasation." (PMID 32308936, 2020). "GAS5 as a ceRNA competes with PDCD4 to bind to miR-21, and the depletion or overexpression of GAS5 could lead to the downregulation or upregulation of PDCD4 levels in tumor cells." (PMID 31620370, 2019). "Moreover, PDCD4 expression in MPM showed a trend from epithelioid to biphasic and sarcomatoid subtypes, suggesting a role in tumor progression and, more specifically, in epithelial-mesenchymal transition (EMT)." (PMID 29707109, 2018). "miR-21, in turn, suppresses the expression of tumor suppressors such as phosphatase and tensin homolog (PTEN), programmed cell death protein 4 (PDCD4), reversion-inducing-cysteine-rich protein with kazal motifs (RECK), and metalloproteinase inhibitor 3 (TIMP3) by direct targeting." (PMID 29538313, 2018). "The tumor progression reduced by hsa-miR-21 down-regulation is mediated by the hsa-miR-21 target genes; the target genes are metastasis-related tumor suppressor genes such as TPM1, Programmed Cell Death 4 (PDCD4) and SERPINB5." (PMID 28793339, 2017). "Also, because its expression is inversely correlated with its target gene programmed cell death 4 (PDCD4), miR-21 is involved in cell migration and tumor invasion." (PMID 28100188, 2017). "KHSRP mainly enhances tumor cell migration and invasion by promoting the maturation of miR-130b, miR-21 and miR-301a and by indirectly inhibiting the expression of their targets, such as endogenous EMT inhibitors BMP6, PDCD4 and TIMP3." (PMID 29254151, 2017). "In the present study we identified a novel stabilizer of tumor suppressor Pdcd4, 1,2-bis(4-chlorophenyl)disulfide (compound 1), which not only stabilized Pdcd4 but also inhibited cellular proliferation." (PMID 26982744, 2016). "Nevertheless, some studies have suggested the conflicting conclusion that PDCD4 does not exert a tumor-suppressing effect in certain malignancies, such as non-small cell lung cancer." (PMID 27852288, 2016). "In this study, we demonstrated that PDCD4 was dramatically downregulated in CRC tissues and could inhibit proliferation and migration and promote apoptosis in CRC cells and attenuate tumor growth in xenografted mice." (PMID 27647131, 2016).
tumor (continued). "The R110 of PDCD4 and the catalytic activity of PRMT5 are necessary for tumor growth." (PMID 27556302, 2016). "We then measured PDCD4 mRNA levels in the same CRC tissue pairs and detected irregular alterations in PDCD4 mRNA levels between the tumor and paired non-tumor tissues." (PMID 27647131, 2016). "Pdcd4 has been well documented as a tumor suppressor, but the possible roles in ADSCs remain lacking." (PMID 27031966, 2016). "Consistent with previous findings, our study supports that miR-21 and PDCD4 have a negative correlation, with miR-21 reducing PDCD4 expression and inducing tumor cell invasion and distant metastasis." (PMID 26252635, 2015). "These oncogenic functions were shown to be regulated by miR-21-mediated downregulation of several established tumor suppressor molecules, including PTEN, programmed cell death 4 (PDCD4), tropomyosin, reversion-inducing cysteine-rich protein with kazal motifs (RECK), and dickkopf 2 (DKK2)." (PMID 26504785, 2015). "Moreover, miR-21, which is overexpressed in CCA, induces posttranscriptional inhibition of both PDCD4 (Programmed Cell Death 4) and 15-PGDH (15-hydroxyprostrangaldin dehydrogenase) and consequently increases the rate of tumor growth." (PMID 26343736, 2015). "Besides miR-21, its target genes of PTEN, PDCD4, RECK were selected, including PTEN as one of the most important tumor suppressors." (PMID 26284486, 2015). "Both PDCD4 and TRAF6 were expressed in the astroglial component of the tumor, and a negative correlation was observed between the PDCD4 IRS and the miR21 (r = −0.817, p = <0.001), as well as between the TRAF6 IRS and the miR146a (r = −0.498, p = < 0.05)." (PMID 25986346, 2015). "miR-21 has been reported as an oncomir that contributes to motility invasion and metastasis by targeting tumor suppressors such as phosphatase and tensin homolog (PTEN), tropomyosin 1, programmed cell death 4 (PDCD4) and mammary serine protease inhibitor (Maspin)." (PMID 25232827, 2014). "Rather than directly affecting transcription, PDCD4 (programmed cell death 4) is a novel tumor suppressor that inhibits protein translation through interaction with the eukaryotic translation initiation factors eIF4A and eIF4G." (PMID 25196934, 2014). "In the present study, we hypothesized that miR-21 downregulates the expression of PDCD4 and PTEN in A431 cells, and that the inhibition of miR-21 subsequently increases PDCD4 and PTEN expression and suppresses tumor cell growth." (PMID 24959246, 2014). "In our cohort we observed a decrease in PDCD4 mRNA levels in the tumours relative to the normal tissues, but no changes as disease progressed by Dukes' stage." (PMID 25310697, 2014). "Since re-introduction of PDCD4 protein into tumor cells is likely not a feasible therapeutic option, we sought to explore if targeting downstream of PDCD4 would offer an effective strategy." (PMID 23965755, 2013). "We observed that Pdcd4 and miR-34a were significantly downregulated, whereas CD24, Src, and miR-21 were significantly upregulated in the tumor tissues as compared to the respective normal tissues (p = 0.003; p = 0.05; p = 0.001; p = 0.05 and p = 0.002; respectively)." (PMID 23533633, 2013). "Other studies have found that miR-21 may promote tumor proliferation and invasion in GC by suppressing the expression of PTEN or PDCD4." (PMID 24040025, 2013). "In order to use this therapeutically to our advantage, we decided to target downstream of PDCD4 since overexpressing a protein in patient tumor samples is likely not a feasible option." (PMID 23965755, 2013). "Programmed cell death protein 4 (Pdcd 4) is a tumor suppressor that is down-regulated or absent in various tumors." (PMID 23469214, 2013). "Furthermore, resveratrol inhibited the expression of the miR-21 target, PDCD4, in PC-3M-MM2-derived tumors from a SCID-mouse tumor model." (PMID 23272133, 2012). "Programmed cell death 4 (Pdcd4) is a novel tumor suppressor that inhibits translation rather than transcription." (PMID 23056346, 2012).
tumor (continued). "Mice expressing high levels of PDCD4 are also more resistant to tumor growth in comparison to normal controls." (PMID 22194833, 2011). "Additionally, another miRNA—hsa-miR-34a—acts as a tumor suppressor, post-transcriptionally downregulating CD24 and SRC, which consequently decreases hsa-miR-21-5p expression and increases the expression of PDCD4 and PTEN." (PMID 40362695, 2025). "MiR-21-5p may be activated by the phosphatidylinositol-3-kinase (PI3K), signal transducer and activator of transcription 3 (STAT3), and programmed cell death factor 4/tumor necrosis factor-α (PDCD4/TNF-α) signaling pathways, which affect inflammatory processes and tumor progression in CRC." (PMID 38584226, 2024). "Therefore, we initially investigated whether the P21-mediated downregulation of oncogenic miR-21 leads to tumor suppressor gene activation, specifically PTEN and PDCD4, and their subsequent downstream signals." (PMID 38994018, 2024). "In addition, future studies should be conducted to verify whether miR-21+/+ mice might become immunized against the tumor after radiotherapy and anti-PD-L1 treatment and how PI3K is phosphorylated by PDCD4." (PMID 35295718, 2022). "However, co-transfection of miRNA-208a-insensive PDCD4 with miRNA-208a decreased the size and weight of the tumour, although total abrogation of tumour growth did not occur, even though apoptosis had increased." (PMID 35847932, 2022). "According to recent research, exercise and hormone treatment decreased tumor growth and angiogenesis in a mouse model of invasive breast cancer by reducing levels of miR-21, ER, HIF-1, VEGF, and raising levels of miR-20 IL-10, let-7a, and PDCD4 in tumor tissue." (PMID 34778378, 2021). "The miR-21 targets include the genespromoting apoptosis (PDCD4 and LRRFIP1), as well as the tumor suppressor genes inhibitinginvasion (RECK and TIMP3) and proliferation(IGFBP3).Furthermore, miR-21 can affect microglial behavior, thus ensuring favorableconditions for tumor growth." (PMID 34707896, 2021). "In intracranial rat tumor models, the complex regressed tumor volume and induced the expression of tumor suppressor genes phosphatase and tensin homolog (PTEN) and programmed cell death protein 4 (PDCD4); which were earlier inhibited in miR21 expressing GB cells." (PMID 35178355, 2021). "Moreover, it has been reported that the over-expression of miR-21 is able to mediate cell survival and proliferation by targeting several potential tumor suppressor genes, like phosphatase and tensin homolog (PTEN), tropomyosin 1 (TPM1) and programmed cell death 4 (PDCD4)." (PMID 33374170, 2020). "Programmed Cell Death 4 (PDCD4) is a tumor suppressor protein whose expression has been shown to correlate with better survival in various cancers; however, upon interaction with PRMT5, PDCD4 becomes methylated at R110 and loses its tumor suppressor activity in MCF-7 cells." (PMID 30613353, 2018). "For instance, miR-21, which is highly expressed at tumor cells and promotes tumor growth by inhibiting the expression of dimethylarginine dimethylaminohydrolase 1 (DDAH1), phosphatase and tension homology deleted on chromosome ten (PTEN), and programmed cell death protein 4 (PDCD4)." (PMID 29027965, 2017). "With regard to the interplay between miR-21 and PDCD4, which was definitely verified by a series of similar studies, that miR-21 was generally overexpressed in cancerous tissues versus paired normal controls, regardless of its tumor types or origins." (PMID 25400316, 2014). "A study of human T98G cells showed that the presence of serum rapidly phosphorylated PDCD4 on Ser67 by the protein kinase p70-S6K and subsequently degraded it via the ubiquitin ligase SCFβ-TrCP, which was confirmed in HEK293 cells exposed to the tumor promoter 12-O-tetradecanoylphorbol-13-acetate." (PMID 24626527, 2014).